CYB5R1 (cytochrome b5 reductase 1)
Description:
Catalyzes the reduction of two molecules of cytochrome b5 using NADH as the electron donor.
Synonyms: b5R.1; NQO3A2; humb5R2; B5R1; B5R2
Tractability: Antibody: its Gene Ontology location is reachable by antibodies, with high confidence; UniProt predicts a signal peptide or a membrane-spanning region. PROTAC: ubiquitination databases record sites on it; its protein half-life has been measured.
Gene: Protein-coding gene on chromosome 1 (202,961,118 to 202,967,277, reverse strand). Ensembl gene ENSG00000159348.
Subcellular location: Membrane
Subcellular location (Human Protein Atlas): Mitochondria; Cytosol
Pathways (Reactome):
Hemostasis: Platelet degranulation
Transport of small molecules: Erythrocytes take up carbon dioxide and release oxygen
Gene Ontology:
Molecular function: protein binding; cytochrome-b5 reductase activity, acting on NAD(P)H; FAD binding; cytochrome-b5 reductase activity, acting on NADH; oxidoreductase activity
Biological process: bicarbonate transport
Cellular component: extracellular exosome; membrane; mitochondrion; endoplasmic reticulum membrane; plasma membrane; platelet alpha granule membrane
Genetic constraint (gnomAD): Loss-of-function variants: 30 observed, 33.78 expected, observed/expected ratio (o/e) 0.89, 90% interval 0.66 to 1.2. The upper end of that interval is the gene's LOEUF score, 1.2, which puts it in group 5 of 6, group 1 being the genes least tolerant of losing a copy. Missense variants: 334 observed, 383.1 expected, observed/expected ratio (o/e) 0.87, 90% interval 0.8 to 0.95. Synonymous variants: 154 observed, 156.09 expected, observed/expected ratio (o/e) 0.99, 90% interval 0.87 to 1.13.
Homologues: Orthologues: chimpanzee CYB5R1 (100% identical), macaque CYB5R1 (98% identical), guinea pig CYB5R1 (94% identical), rabbit CYB5R1 (92% identical), mouse Cyb5r1 (92% identical), dog CYB5R1 (91% identical), pig CYB5R1 (89% identical), rat Cyb5r1 (77% identical), tropical clawed frog cyb5r1 (58% identical). Paralogues in human: CYB5R3 (60% identical), CYB5R2 (52% identical), CYB5R4 (30% identical), CYB5RL (27% identical), OXNAD1 (18% identical).
Diseases named in the same sentence as CYB5R1 in open-access papers:
CYB5R1 is named in the same sentence as 14 diseases in open-access papers, as found by Europe PMC text mining. Sharing a sentence is not in itself a finding about the gene and the disease. The quoted sentences say what the papers report.
colorectal cancer (2 papers, 2016 to 2022). A primary or metastatic malignant neoplasm that affects the colon or rectum. "Since EMT is linked to migratory and invasive tumor cell phenotypes in colorectal cancer, we next assessed the effects of CYB5R1 depletion on these malignant traits of colon cancer cells." (PMID 27120783, 2016). "Furthermore, we demonstrate that CYB5R1 is required for an infiltrative tumor cell phenotype, and robustly linked with poor prognosis in colorectal cancer." (PMID 27120783, 2016). "Given CYB5R1’s reported role in ferroptosis and colorectal cancer, therapeutics targeting CYB5R1 could be beneficial in treating those suffering from certain cancers." (PMID 36441026, 2022). "Our findings not only indicate high biomarker potential of CYB5R1, but importantly identify a potential drug target in tumor cells undergoing EMT at the infiltrative tumor edge of colorectal cancer." (PMID 27120783, 2016).
atherosclerosis (1 paper, 2025). A disease characterized by the build-up of fatty material and calcium deposition in the arterial wall resulting in partial or complete occlusion of the arterial lumen. "In summary, these findings reveal that CYB5R1 establishes a redox relay with CoQ10 at the outer mitochondrial membrane to protect endothelial cells from ferroptosis and atherosclerosis." (PMID 41256004, 2025). "To further investigate the relationship between CYB5R1 and atherosclerosis, we generated global CYB5R1 and endothelial cell specific CYB5R1 knockout mice." (PMID 41256004, 2025). "Additionally, its efficacy may be further compromised in disease settings such as atherosclerosis, where reduced CYB5R1 expression can impair quinone redox cycling and exacerbate ferroptosis." (PMID 41256004, 2025).
colon cancer (1 paper, 2016). "We treated DLD-1 and HCT116 colon cancer cell lines with siRNAs specifically directed against CYB5R1 mRNA, which resulted in reduction of CYB5R1 protein levels in both cell lines, when compared to control siRNA treatment." (PMID 27120783, 2016). "Since infiltrative colon cancer cells at the leading tumor edge are known to partially lose their epithelial phenotype, we next analyzed CYB5R1 expression and the expression of the epithelial cell adhesion protein E-Cadherin in individual cases by confocal immune fluorescence." (PMID 27120783, 2016). "While this suggests that colon cancer cells with high CYB5R1 expression undergoing EMT are highly metabolically active, specifically resistant to apoptosis, and protected from carcinogenic mutagens, our findings have important implications for a potential targetability of this tumor cell subset." (PMID 27120783, 2016). "Collectively, we here demonstrate an important link of CYB5R1, EMT and colon cancer progression that might be exploited for diagnostic and eventually therapeutic purposes in CRC patients." (PMID 27120783, 2016). "Finally, to independently validate these findings, we tested for clinical correlations of CYB5R1 mRNA levels in the TCGA data set of 457 colon cancers." (PMID 27120783, 2016). "Moreover, markers that induce or indicate EMT in colon cancer were significantly overexpressed in tumors with high CYB5R1 levels, including ZEB1 (r=0.20, p<0.0001), TWIST1 (r=0.22, p<0.0001), and VIM (r=0.29, p<0.0001)." (PMID 27120783, 2016). "Here, we establish CYB5R1 as a potential marker for CRC cells of an infiltrative EMT like tumor cell phenotype which can be used to easily visualize this tumor cell subset in situ by immunostaining in primary colon cancer tissues." (PMID 27120783, 2016). "Moreover, since our in vitro data suggested dependence of migratory and invasive colon cancer cell phenotypes on CYB5R1 expression, inhibition of this enzyme may as well hold potential for therapeutic intervention." (PMID 27120783, 2016). "Here, we identify CYB5R1, an enzyme involved in oxidative stress protection and drug metabolism, as an indicator of EMT in colon cancer." (PMID 27120783, 2016). "To further examine a possible link of CYB5R1 and EMT in colon cancer, we analyzed independent gene expression data of 457 colon cancer cases from The Cancer Genome Atlas (TCGA)." (PMID 27120783, 2016). "We then seeded cells with and without CYB5R1 depletion in Boyden Chamber assays, and observed considerable decreases in transwell migration and invasion of both cell lines, while these effects were more pronounced in HCT116 than in DLD-1 colon cancer cells." (PMID 27120783, 2016). "This not only implies that CYB5R1 may be specifically useful to determine the overall degree of EMT and cellular plasticity of individual colon cancers, regardless of its intratumoral distribution." (PMID 27120783, 2016).
diabetic retinopathy (1 paper, 2022). "Beyond cancer, CYB5R1 transcript levels are significantly upregulated in retina samples collected from patients with diabetic retinopathy, a disease characterized by aberrations in the retinal microvasculature and blindness." (PMID 36441026, 2022). "By investigating a gene co-expression network in a human diabetic retinopathy dataset, the authors further surmise that CYB5R1 is acting on complex 1 of the electron transport chain." (PMID 36441026, 2022). "This suggests that CYB5R1 might be involved in mitochondrial oxidative stress pathways that factor into the development of diabetic retinopathy." (PMID 36441026, 2022).
gastric cancer (1 paper, 2023). A primary or metastatic malignant neoplasm involving the stomach. "Parallel to our findings, lower CYB5R1 expression in gastric cancer is associated with extended survival rates by fostering normal cellular energy metabolism and decelerating the transformation process from intestinal metaplasia to cancer." (PMID 37752199, 2023).
Hyperglycemia (1 paper, 2023). An increased concentration of glucose in the blood. "We overexpressed different isoforms of CYB5R1 mRNA with short or long 3′UTRs in human podocytes under hyperglycemia condition to compare the mRNA and protein expression differences." (PMID 36747266, 2023).
lung carcinoma (1 paper, 2024). "Neither CYB5R1 nor CYB5R2 was detected in human lung cancer cells." (PMID 38253797, 2024).
melanoma (1 paper, 2019). A malignant, usually aggressive tumor composed of atypical, neoplastic melanocytes. "Similarly, the up-regulated genes in the ABCB5 CTC fractions were involved in metastasis (CALU, CYB5R1, DUSP3, CREG1, ENDOD1), tumour growth, and/or melanoma biology (H1F0, SCNA, WIPI1, TXN2)." (PMID 30769764, 2019).
cancer (3 papers, 2016 to 2023). A tumor composed of atypical neoplastic, often pleomorphic cells that invade other tissues. "Since EMT is strongly implicated in carcinoma progression, we tested for clinical relevance of CYB5R1 expression in CRC." (PMID 27120783, 2016). "EMT is considered regulator of invasion and metastasis and thus cancer progression, and our data on CYB5R1 provide additional evidence for this concept." (PMID 27120783, 2016). "Normal colonic mucosa, adjacent to cancer tissues, demonstrated faint CYB5R1 expression that was confined to few epithelial cells at the crypt base (data not shown)." (PMID 27120783, 2016). "Again, Kaplan-Meier statistics revealed significantly worse cancer specific survival and marginally worse disease free survival of CYB5R1 positive cases." (PMID 27120783, 2016). "The link between CYB5R1 and ferroptosis could also be important in various cell types, especially primary cells, and outside the realm of cancer research." (PMID 36441026, 2022). "Using ROC curve analyses, we determined an optimal cutoff score of 584.5 normalized mRNA reads, and dichotomal classification of cases by this score revealed a strong positive correlation of high CYB5R1 expression and poor cancer specific survival in Kaplan-Meier statistics." (PMID 27120783, 2016). "Importantly, in both case collections, poor survival prediction by CYB5R1 protein or mRNA was independent of other key clinical variables, and thus could be useful to complement cancer staging, when evaluating patient prognosis." (PMID 27120783, 2016).
tumor (2 papers, 2016 to 2019). "Including these variables into a proportional hazards regression analysis revealed that CYB5R1 positivity was an independent predictor of poor tumor specific survival in CRC, indicating a high relative risk (hazard ratio 8.5)." (PMID 27120783, 2016). "CYB5R1 apparently overcomes some of these restrictions by most strongly labelling tumor cells at the leading tumor edge, with little or absent expression in surrounding stromal cells." (PMID 27120783, 2016). "Moreover, CYB5R1 expression directly links EMT and poor prognosis in this tumor entity." (PMID 27120783, 2016).
adenocarcinoma (1 paper, 2024). A common cancer characterized by the presence of malignant glandular cells. "In moderate and poor adenocarcinomas, the expression of the CYB5R3 gene, but not CYB5R1 and CYB5R2/4, was decreased." (PMID 38791014, 2024).
CYB5R1 also shares sentences with these, for which no sentence is quoted: brain glioma (1 paper); psoriasis (1); viral infection (1).